MALAT1 (metastasis associated lung adenocarcinoma transcript 1)
Diseases named in the same sentence as MALAT1 in open-access papers (continued):
Sharing a sentence is not in itself a finding about the gene and the disease.
diffuse large B-cell lymphoma (18 papers, 2017 to 2025). "MALAT1 overexpression in diffuse large B-cell lymphoma cells (DLBCL) limits effector CD8+ T-cell functions by suppressing their proliferation and inducing apoptosis." (PMID 37345170, 2023). "For example, the lncRNA MALAT1 adsorbs miR195 and promotes the development of diffuse large B-cell lymphoma and immune evasion." (PMID 36755298, 2023). "A recent study reported that lncRNA MALAT1 promoted tumorigenesis and immune escape of diffuse large B cell lymphoma by sponging miR-195 to induce apoptosis of CD8+ T cells." (PMID 36693898, 2023). "LncRNA MALAT1 upregulated the expression of PD-L1 via sponging miR-195, leading to promotion of tumorigenesis in diffuse large B cell lymphoma." (PMID 36212476, 2022). "LncRNA MALAT1 promotes tumorigenesis and immune escape of diffuse large B cell lymphoma by promoting PD-L1 capable of enhancing the tumorigenesis and immune escape abilities of cancers." (PMID 31533774, 2019). "Furthermore, MALAT1 is upregulated in the EBV-associated cancers NPC and diffuse large B cell lymphoma (DLBCL), promoting tumorigenesis." (PMID 40733622, 2025). "MALAT1 also showed distinctively high expression when compared to the other lncRNAs tested in cell lines derived from patients with various types of T and NK cell lymphomas and a cell line derived from a patient with diffuse large B-cell lymphoma." (PMID 28412742, 2017). "In diffuse large B-cell lymphoma (DLBCL), MALAT1 upregulates, through miR-195, the expression of PD-L1 and promotes migration and immune escape, with CD8+ T cells mediated." (PMID 33808190, 2021). "In diffuse large B-cell lymphoma (DLBCL), MALAT1 was highly expressed." (PMID 30266744, 2018). "In addition, we analyzed MALAT1 expression in 6 paired CLL and their clonally related transformation to diffuse large B cell lymphoma (Richter transformation, RT) (CLL#2 series)." (PMID 37803049, 2023). "In diffuse large B-cell lymphoma (DLBCL), MALAT1 could sponge miR-195 to upregulate the expression of PD-L1, thus promoting migration and immune escape by regulating proliferation and apoptosis of CD8+ T cells." (PMID 31850199, 2019).
endothelial dysfunction (18 papers, 2018 to 2026). In vascular diseases, endothelial dysfunction is a systemic pathological state of the endothelium (the inner lining of blood vessels) and can be broadly defined as an imbalance between vasodilating and vasoconstricting substances produced by (or acting on) the endothelium. "The MALAT1/miR-320a axis may be associated with the beneficial effects of exercise on endothelial function in obese children and adolescents, as evidenced by their correlation with markers of endothelial dysfunction." (PMID 40463932, 2025). "The findings of this study further uncover the mechanisms underlying the beneficial effects of exercise on endothelial dysfunction, and the MALAT1/miR-320a axis may provide novel targets for the improvement of endothelial function in obese children and adolescents." (PMID 34123418, 2021). "Collectively, these findings identify MALAT1 as a protective regulator that mitigates endothelial dysfunction, vascular remodeling, and PH in SCD, at least in part through the induction of HMOX1." (PMID 41597229, 2026). "A study examines the correlation between MALAT1 and miR-320a and the improvement of endothelial dysfunction in obese children and adolescents, emphasizing the potential protective benefits of exercise." (PMID 40463932, 2025). "lncRNAs such as ANRIL, MEG3, HOTAIR, and MALAT1 regulate vascular smooth muscle cell proliferation, endothelial dysfunction, and angiogenesis in COPD." (PMID 39201688, 2024). "Silencing MALAT1 in CMECs perturbates mitochondrial function and enhances apoptotic pathways, thus aggravating endothelial dysfunction in acute and chronic settings." (PMID 35407662, 2022). "The MALAT1/miR-320a axis regulates endothelial dysfunction and plays a vital role in endothelial cell reconstitution." (PMID 36419933, 2022). "The expression of MALAT1 and miR-320a was correlated with the changes in the anthropometric and blood indices of obese children and adolescents, and their correlations with endothelial dysfunction markers were obtained." (PMID 34123418, 2021). "This study aimed to investigate the relationship of long noncoding RNA MALAT1 and microRNA-320a (miR-320a) with the exercise-induced improvement of endothelial dysfunction in obese children and adolescents." (PMID 34123418, 2021). "Similar to the correlation results of MALAT1 with markers of endothelial dysfunction, we also found the correlation of miR-320a with endothelial dysfunction markers." (PMID 34123418, 2021). "In the present study, we found the decreased levels of MALAT1 in obese children and adolescents after exercise, and exercise-induced changes in MALAT1 expression were positively correlated with the levels of endothelial dysfunction markers." (PMID 34123418, 2021). "All the data revealed that exercise has significantly protective effects against endothelial dysfunction and can regulate the expression of the MALAT1/miR-320a axis." (PMID 34123418, 2021). "In this study, we determined the roles of the MALAT1/miR-181b/TOX signaling pathway in the setting of AS in cases of oxLDL-induced endothelial dysfunction." (PMID 31949884, 2019). "Exercise training diminishes levels of VCAM-1, ICAM-1, and E-selectin in obese children and adolescents, suppresses MALAT1 expression, and elevates miR-320a expression, indicating that physical activity may safeguard against endothelial dysfunction." (PMID 40463932, 2025). "MALAT1 and miR-320a were correlated with endothelial dysfunction markers, indicating that the MALAT1/miR-320a axis may be related with the alleviating effects of exercise on endothelial function in obese children and adolescents." (PMID 34123418, 2021). "We presented the interactions among MALAT1, TOX, and miR-181b in oxLDL-induced endothelial dysfunction." (PMID 31949884, 2019).
endothelial dysfunction (continued). "Functional studies revealed that MALAT1 depletion increased, while MALAT1 overexpression decreased, the endothelial dysfunction markers endothelin-1 (ET-1) and vascular cell adhesion molecule-1 (VCAM1), indicating a protective role of MALAT1 in maintaining endothelial homeostasis." (PMID 41597229, 2026). "For example, we have shown in DR, that ANRIL regulates VEGF, H19 inhibits inflammatory responses and prevents endothelial dysfunction, HOTAIR promotes angiogenesis, oxidative stress and mitochondrial dysfunction, and MALAT1 regulates inflammation via modulation of epigenetic regulators." (PMID 40271126, 2025). "However, the crosstalk between MALAT1, miRNAs, and downstream targets with respect to oxLDL-induced endothelial dysfunction is still not well defined." (PMID 31949884, 2019).
Hypertension (17 papers, 2017 to 2024). The presence of chronic increased pressure in the systemic arterial system. "In southern Chinese populations, genetic polymorphisms in MALAT1 have been associated with an increased risk of hypertension development." (PMID 38791545, 2024). "Since hypertension is a commonly associated cardiovascular comorbidity with ageing it will be interesting to determine if MALAT1 has differential roles depending on the circumstances and disease conditions." (PMID 37034355, 2023). "Notably, MALAT1 expression was elevated in hypertensive rats, suggesting its potential as a diagnostic marker for hypertension." (PMID 39502508, 2024). "Both MIAT and MALAT1 expressionlevels were associated with hypertension and premature CAD." (PMID 31188931, 2019). "Elevated levels of MALAT1 expression in hypertension imply its potential abnormal expression in this disease." (PMID 38791545, 2024). "Further studies on the role of MALAT1 in the proliferation and apoptosis of HUVECs have provided insights into its potential therapeutic implications in hypertension." (PMID 39502508, 2024). "Recent research has shown that reducing MALAT1 levels can decrease the concentrations of proinflammatory cytokines such as TNF-α, IL-6, and IL-1β, which are closely associated with hypertension." (PMID 39502508, 2024). "This review explores the potential role of the lncRNA MALAT1 in controlling the Keap1-Nrf2-antioxidant defense pathway in salt-induced hypertension." (PMID 38791545, 2024). "The lncRNA MALAT1 plays a crucial role in regulating various pathological conditions, including hypertension, tumors, immunomodulatory disorders, aging, and wound healing, as extensively investigated and documented." (PMID 38791545, 2024). "Recent studies have highlighted the role of MALAT1 in hypertension, particularly in vascular lesions and remodeling in hypertensive mice." (PMID 39502508, 2024). "Recent studies have also highlighted MALAT1's role in obesity, dysregulated glucose homeostasis, dyslipidemi, and hypertension, collectively termed MetS." (PMID 39502508, 2024). "Several studies have shown that MALAT1 targets different genes and miRNAs that play a key role in the pathophysiology of hypertension and other disorders whose dysregulation is strongly associated with different pathological outcomes." (PMID 38791545, 2024). "White-coat hypertension, characterised by increased clinic BP, similarly showed significant upregulation of MALAT1, suggesting its potential use as a biomarker for the diagnosis of hypertension." (PMID 38791545, 2024). "MALAT1 enhances the levels of proinflammatory cytokines (IL-18 and IL-1β) in pregnancy-induced hypertension by activating the NF-κB pathway." (PMID 35626352, 2022). "Our findings highlight the potential avenues that lncRNA MALAT1 holds for future development of therapeutic strategies for hypertension." (PMID 31619581, 2019). "In the current study, we aim to demonstrate the important role played by lncRNA MALAT1 on cardiac remodeling in hypertension." (PMID 31619581, 2019). "The lncRNA MALAT1 modulates miR-150-5p/ET1 to control pregnancy-induced hypertension." (PMID 38791545, 2024). "In this review, we have compiled a body of evidence to examine the impact of MALAT1 on hypertension and CVD, elucidating its roles in inflammation responses and mechanistic approach via the Keap1-Nrf2 pathway modulates antioxidant defense in salt-sensitive hypertension." (PMID 38791545, 2024). "Although long non-coding RNA (lncRNA) metastasis associated lung adenocarcinoma transcript 1 (MALAT1) has been identified to play important roles in the development of cardiovascular diseases, the regulatory function of lncRNA MALAT1 in hypertension remains poorly understood." (PMID 31619581, 2019). "Thus, MALAT1, acting via the Keap1-Nrf2 pathway, modulates antioxidant defense in hypertension." (PMID 38791545, 2024).
Hypertension (continued). "However, additional efforts are necessary to investigate whether lncRNA MALAT1 regulates MyoD activity during hypertension via modulation of TGF-β1 activity or other molecular mechanisms to successfully elucidate the therapeutic use of lncRNA MALAT1." (PMID 31619581, 2019). "Another study finds that lncRNA MALAT1 controls the growth, movement, and phenotypic change of vascular smooth muscle cells (VSMCs) through the miR-145-5p/HK2 axis in hypertension." (PMID 38791545, 2024). "Other variables that were also predictive but not as strongly included smoking, male sex, weight, and hypertension (positive correlation) and MALAT1 (T >C ) (negative correlation)." (PMID 35053285, 2022). "The lipid profile, and to a lesser extent smoking status, male sex, weight, hypertension, and MALAT1 (T > C) (negative correlation), explained the variance between patients/control groups via a principal component analysis." (PMID 35053285, 2022). "Hsa‐miR‐135a‐5p has a negative correlation with lncRNA MALAT1 in hypertension." (PMID 36149748, 2022).
pulmonary arterial hypertension (17 papers, 2019 to 2026). Pulmonary arterial hypertension (PAH) is a group of diseases characterized by mean pulmonary artery pressure >20 mmHg and elevated pulmonary arterial resistance leading to right heart failure. "Furthermore, MALAT1 dysregulation has been linked to numerous human disorders, including gastric cancer and pulmonary arterial hypertension." (PMID 38791545, 2024). "Additionally, by directly regulating miR-214, the MALAT1 rs619586 G allele is associated with a higher risk of pulmonary arterial hypertension." (PMID 31942979, 2020). "In addition, MALAT1 has also been proved to induce pulmonary arterial hypertension susceptibility in Chinese people." (PMID 31619581, 2019). "Plasma levels of MALAT1 are significantly elevated in patients with pulmonary arterial hypertension (PAH)." (PMID 38791545, 2024). "A study of pulmonary hypertension found that the level of Malat1 was significantly increased in hypoxic human pulmonary artery SMCs, and Malat1 depletion inhibited SMC migration and proliferation." (PMID 37022488, 2023). "KLF5 is also a target gene of metastasis-associated lung adenocarcinoma transcript 1 (MALAT1); the MALAT1/hsa-miroRNA (miR)-124-3p.1/KLF5 axis is pivotal in cell cycle progression of pulmonary artery hypertension." (PMID 33493334, 2021). "A MALAT1 antagonist active in vivo might reduce occlusive lesions in pulmonary arterial hypertension or inhibit airway epithelial cell proliferation." (PMID 33287230, 2020). "In addition, the alteration of lncRNA MALAT1 could up‐regulate the expression of X box‐binding protein by functioning as a ceRNA for miR‐124, which contributes to pulmonary arterial hypertension." (PMID 32410228, 2020). "Malat1 interacts with miR‐124‐3p.1/KLF5 to enhance the remodeling of pulmonary vasculature and facilitate the progression of cell cycle in pulmonary artery hypertension." (PMID 39491316, 2024). "LincRNA MALAT1 (metastasis-associated lung adenocarcinoma transcript 1, also termed LINC00047) has rs619586 A > G variant, which is significantly associated with the susceptibility of pulmonary arterial hypertension (PAH), and the carriers with variant G genotypes have a decreased PAH risk." (PMID 32523949, 2020). "Furthermore, a previous study indicated that lncRNA MALAT1 could induce myocardial fibrosis and pulmonary vascular remodeling of pulmonary artery hypertension; however, the effects of lncRNA MALAT1 on thoracic aorta and myocardial remodeling of hypertensive rats remain to be explored." (PMID 31619581, 2019). "It was previously discovered that the binding of miR-124-3p, MALAT1, and KLF5 could modulate pulmonary artery hypertension development, and MALAT1 was positively correlated to KLF5." (PMID 36243708, 2022).
renal fibrosis (17 papers, 2020 to 2024). A final common manifestation of a wide variety of chronic kidney diseases characterized by glomerulosclerosis and tubulointerstitial fibrosis. "In this study, we first displayed the increased lncRNA metastasis-associated lung adenocarcinoma transcript 1 (MALAT1) expression in renal fibrosis in patients with obstructive nephropathy (ON)." (PMID 32203053, 2020). "Fortunately, DHA has been shown to effectively attenuate renal fibrosis caused by ON through the MALAT1/miR-145/FAK axis in vivo and in vitro." (PMID 32203053, 2020). "Accumulating evidence indicates that the expression of MALAT1 is dysregulated in DN and it plays an important role in promoting renal fibrosis in DN." (PMID 36760471, 2023). "The MALAT1/miR-145/focal adhesion kinase (FAK) pathway has been noted to assume a significant role in TGF-β1-induced renal fibrosis." (PMID 35534472, 2022). "In another study, the m6A-mediated MALAT1/miR-145/FAK pathway was found to be involved in renal fibrosis." (PMID 35372359, 2022). "In summary, these results revealed that m6A modification participated in the upregulation of MALAT1 in renal fibrosis." (PMID 32203053, 2020). "Of mention above, we displayed an increased expression of MALAT1 in clinicopathological specimen of renal fibrosis." (PMID 32203053, 2020). "This, therefore, disturbed the feedback loop between MALAT1 and β-catenin in normal conditions, and culminated in accelerated podocytes injury and renal fibrosis." (PMID 32752143, 2020). "qPCR analyses illustrated that MALAT1 expression was increased in renal fibrosis tissues compared to that in normal tissues." (PMID 32203053, 2020). "Next, MALAT1/miR-145/focal adhesion kinase (FAK) pathway was confirmed to play an importment role in TGF-β1-induced renal fibrosis." (PMID 32203053, 2020). "Knockdown of MALAT1 in STZ-induced rats improved the kidney pathology and inhibited the expressions of col I, col IV, FN, and LN in renal tissues, which demonstrated that MALAT1 may be related to renal fibrosis." (PMID 36760471, 2023). "MALAT1 leads to the promotion of renal fibrosis in patients with obstructive nephropathy (ON)." (PMID 35534472, 2022). "In conclusion, MALAT1 overexpression may enhance renal fibrosis in diabetic rats and cell damage in HG-induced HK-2 cells via the miR-2355-3p/IL6ST axis, which provides a new perspective of DN treatment." (PMID 33995063, 2021). "In conclusion, these findings demonstrated that lncRNA MALAT1 might enhance renal fibrosis in diabetic rats and cell damage in HG-induced HK-2 cells via the miR-2355-3p/IL6ST axis." (PMID 33995063, 2021). "LncRNA MALAT1 could be attributed severe podocyte damage via its interplay with β-catenin, a key mediator of podocyte injury and renal fibrosis." (PMID 33859515, 2021). "In this study, we investigated the mechanism of MALAT1 in ON-induced renal fibrosis." (PMID 32203053, 2020). "In addition, the MALAT1/miR-145/FAK pathway was involved in the effect of dihydroartemisinin (DHA) on TGF-β1-induced renal fibrosis in vitro and in vivo." (PMID 32203053, 2020). "To dissect whether MALAT1 is involved in the progression of renal fibrosis in patients with ON, we measured MALAT1 expression in renal fibrotic tissues in patients with ON." (PMID 32203053, 2020). "Moreover,MALAT1 is involved in podocyte damage and renal fibrosis." (PMID 37272835, 2023). "Conclusively, our study revealed that QHYS significantly reduced proteinuria, alleviated renal fibrosis, and attenuated the podocyte EMT in DN rats, which may be associated with the downregulation of lncRNA MALAT1 expression and inhibition of the Wnt/β-catenin pathway." (PMID 36760471, 2023). "Our result showed that MALAT1 could absorb miR-2355-3p to accelerate HG-induced renal fibrosis." (PMID 33995063, 2021). "In addition, we revealed that activating the MALAT1/miR-145/FAK ceRNA network could increase TGF-β1-induced renal fibrosis in vitro and significantly altered MALAT1, miR-145 and FAK expression in vivo." (PMID 32203053, 2020).